CLU (clusterin)
Diseases named in the same sentence as CLU in open-access papers (continued):
Sharing a sentence is not in itself a finding about the gene and the disease.
cancer (continued). "Various potent inhibitors of CLU, including OGX-011 and RNA interference (RNAi) agents, have been developed for use in cancer therapies, yielding encouraging therapeutic outcomes in patients." (PMID 38667280, 2024). "Clusterin (CLU) is a stress-activated, ATP-independent molecular chaperone, normally secreted from cells, and can promote cancer development by regulating cell proliferation, apoptosis, and cycle." (PMID 37553571, 2023). "We found that apoptosis-related genes URI1, PAK2, PARP1, CLU, and TIMP3 were significantly upregulated in multiple cell populations of cancer cells." (PMID 37124501, 2023). "Verteporfin inhibits the clusterin gene expression in those GC stem cells and suppresses its viability and growth in vivo, indicating that clusterin-targeted therapy and verteporfin therapy may be useful in repressing cancer growth by HSP90 function regulation." (PMID 36615513, 2022). "We discovered that CAFs estimated infiltration among TCGA cancers CESC, PRAD, COAD, HNSC, TGCT, HNSC-HPV-, LGG, BLCA, READ, and YHYM examined using all methods was statistically favorably connected to CLU expression." (PMID 36685863, 2022). "This study aimed to examine the function of CLU gene, which was retrieved from the tongue squamous carcinoma dataset, in OSCC, HNSC, and diverse human cancers." (PMID 36685863, 2022). "Western blotting data analysis confirmed the upregulation of CLU, ITIH4, SERPINC1, and C1RL in endometrial and exosome cancer sera compared to those of control subjects." (PMID 34298850, 2021). "In Elyada’s scRNA-seq analysis, ductal cancer cells in human PDAC were clustered in two major subtypes: the classic (by TFF1, TFF2, LYZ, VSIG2, and CEACAM6 marker genes) and secretory (by SPP1, CLU, CTGF, and COL18A1 marker genes) subtypes." (PMID 34035226, 2021). "IPA analysis indicated that pathways of LXR/RXR activation and FXR/RXR activation were most significantly activated, in which APOH, CLU, and ITIH4 were involved in cancer, organismal injury and abnormalities, and reproductive system disease." (PMID 33299887, 2020). "While this study identifies that YB-1, Hsp27 and CLU all localize in TNTs, only CLU and YB-1 positively regulate TNT biogenesis in cancer cells." (PMID 31127190, 2019). "Clusterin (CLU), a unique chaperone protein with analogous oncogenic criteria to HSPs, has also been proven to confer resistance to anti-cancer drugs." (PMID 31540420, 2019). "Of the differentially expressed proteins, CLU, NDRG1, CD166, S100A11 and Galectin-1 were carcinoma-related proteins affected by rGal3C." (PMID 28701735, 2017). "One example involves the molecular chaperone, clusterin (CLU), which is expressed in many human cancers, including PCa, where it increases following castration to become highly expressed in CRPC." (PMID 27198502, 2016). "To select the cell lines with a high level of CLU expression, we used western blot analysis to analyze the Clusterin expression at the protein levels in HO8910, HO8910PM, OVCAR-3 and TOV-21G cancer cell lines." (PMID 26293319, 2015). "A positive correlation between expression level of CLU and early HCC recurrence was found and suggested that cancer cells with high expression of CLU have more invasive phenotype." (PMID 25609201, 2015). "A subset of the targets (BCL2, CLU, HSPB1, BIRC5, EIF4E and RRM2) is being investigated for cancers in combination with approved cytotoxic drugs." (PMID 22989709, 2012). "On the other hand, the most frequently down regulated AM genes are TGFBR2 (7/13 of cancer models), BAG3, CLU, LGALS1, LTBR, SGK (in 6/13)." (PMID 19402918, 2009). "In the present study, we demonstrated the correlative expression of ACT, CLU, HAP, AAT and LRG in patients with EOCa in accordance to the three initial stages of the cancer by using the gel-based proteomics approach." (PMID 19709441, 2009).
cancer (continued). "This study, using dedicated-microarrays containing 6864 genes previously known to be involved in cancer, allowed us to select 5 genes (LGALS4, ACS5, CLU, SRI and CCT5) with significant differential expression between tumors and normal tissue." (PMID 19903339, 2009). "Like CLU, CPL is another protein reported to be elevated in sera of patients with diverse types of cancer." (PMID 18637207, 2008). "Semiquantitative analysis indicates that most of samples from different types of cancer have strong, high percentage of BID immunoreaction, while normal tissues only show low to medium level of staining; CLU tends to be down-regulated in tumors." (PMID 17989776, 2007). "Tissue microarray analysis (TMA) was also performed for three randomly picked common cancer genes (SPP1, BID and CLU) to determine if mRNA changes were correlated with changes in protein expression in cancer patients." (PMID 17989776, 2007). "Therefore, to clarify the cardioprotective versus oncogenic potential of clusterin, future research should investigate its expression patterns and functional effects on both EVSASC-treated cardiomyocytes and cancer cells." (PMID 40671119, 2025). "Decreased activity of the phosphatidylinositol 3′-kinase (PI3K)/AKT signaling pathway, comprising the extracellular stress protein clusterin and IGF1, under external stimuli is another mechanism thought to be involved in the switching between cancer cell proliferation and dormancy." (PMID 36430404, 2022). "Moreover, it was demonstrated that semen clusterin is not only a promising ligand for DC-SIGN in cancer, it also abolishes the binding of HIV-1 to DC-SIGN by high-affinity binding fucose-rich glycans on semen clusterin to DC-SIGN." (PMID 34638920, 2021). "Clusterin is not detected in normal tissue, but overexpressed in many cancer tissues or cells; therefore, the apparent ubiquitous presence of clusterin has the potential for it to be used as a biomarker for health and in disease." (PMID 33356806, 2021). "Consistently, when CLU and PRKD3 protein expression level in TNBC sample were quantified and analyzed, both CLU and PRKD3 protein levels are significantly elevated in TNBC cancer tissues compared to paracancerous tissues, and are significantly positively correlated." (PMID 33643800, 2021). "CLU mRNA is downregulated in the vast majority of naïve cancers according to Oncomine® database, and PCa does not make exception." (PMID 31885575, 2019). "Next, we observed a positive correlation between CLU and EIF3I in HCC samples, supporting the notion that CLU-EIF3I complex may function as a cooperative unit in cancer cells." (PMID 25609201, 2015). "The present study identified the different altered expression of LRG, CLU and KNG in the urine of a group of patients with early stage OCa, which may be used as complementary biomarkers for early detection of the cancer." (PMID 23579955, 2013). "Although CLU expression has been associated with various human malignancies, the mechanisms by which CLU promotes cancer progression and metastasis have not been elucidated." (PMID 22949882, 2012). "Notably, CLU mRNA levels were highly correlated with reduced NADPH oxidase activity and negative regulation of ferroptosis in HNSCC, indicating that CLU potentially reduces ROS production in cancer cells." (PMID 39905539, 2025). "The lack of research concerning CLU isoforms in OSCC calls for more evidence to establish correlations and explore their diagnostic or prognostic potential as well as therapeutic targets for effective cancer therapy." (PMID 37239129, 2023). "However, no pan-cancer study has evaluated the link between CLU expression and tumorigenesis/clinical prognosis." (PMID 36685863, 2022). "Therefore, the cancer cell fate between dormancy and proliferation during tumor progression could be dictated by the interplay between IGF-1 and clusterin." (PMID 36430404, 2022).
cancer (continued). "Although this shorter CLU isoform has low abundance in cells or is not expressed at all44, expression is upregulated in cancer cell lines by stress and following induction of the cell death cascade, suggesting a role for these proteins in mediating cellular response to stress." (PMID 36329114, 2022). "In addition to cancer regions, sample 2 could also distinguish regions of breast ductal epithelial cells (cluster 6) with high expression levels of PTN, RGS2, CLU, and KRT15." (PMID 34799559, 2021). "So, for instance, in cancer it may not be the overall rise in clusterin levels that determines its role but the altered location of clusterin proteins resulting in an increased ratio of sCLU to intracellular CLU." (PMID 30872998, 2019). "However, an increased level of CLU expression may not be solely responsible for the development of cancer." (PMID 37239129, 2023). "CLU is a secreted protein that can be secreted by tissues into body fluids, and this study indicates that CLU is overexpressed in CCA tissues; in addition, bile is the body fluid adjacent to CCA tissues, so the elevated bile CLU concentrations in CCA patients may be secreted from the cancer tissues." (PMID 37553571, 2023). "The expression of PIGR, DEFB1, LTF, CLU, SCGB2A1 and S100A7, while having a positive role in cancer elimination, were either downregulated or not changed in all or some of the BC subtypes." (PMID 38589404, 2024). "An overall increase in CLU expression may not be the critical factor in cancer, instead it is thought that an altered ratio of intracellular: secreted CLU proteins may be the key factor, such that cancer is accompanied by an increase in CLU secretion and a reduction in intracellular CLU." (PMID 30872998, 2019). "Instead of co-localizing with LC3 punta after treatment stress, this CLU–LIR mutant remained dispersed and failed to cytoprotect cancer cells." (PMID 25503391, 2014).
neurodegenerative disease (44 papers, 2008 to 2025). A disorder of the central nervous system characterized by gradual and progressive loss of neural tissue and neurologic function. "A crucial and interesting feature of CLU is its upregulation in severe physiological disorders and various neurodegenerative diseases that are often associated with advanced aging." (PMID 39253532, 2024). "In the following sections, select chaperones will be described that have been clearly identified as causative agents in neurodegenerative diseases: clusterin, progranulin, and BRICHOS domain-containing proteins." (PMID 33192447, 2020). "The most dysregulated KEGG pathway in CLU knockout neurons compared to CLU wild type was the AD pathway (p = 0.000004), with other gene sets linked to neurodegenerative diseases also significantly dysregulated." (PMID 30090055, 2018). "Our data lend further support to the contribution of rare coding CLU mutations in the pathogenesis of neurodegenerative diseases." (PMID 26179372, 2015). "APOE, CST3, and CLU are known to be mainly involved in all three neurodegenerative diseases and, in particular, have a function of binding to amyloid-β or tau protein, indicating an association with features of neurodegenerative diseases due to protein aggregation of misfolded proteins." (PMID 36797805, 2023). "This research has consistently reinforced that clusterin’s ability to bind to and inhibit the formation of amyloid fibrils is a key mechanism of action, particularly in neurodegenerative diseases." (PMID 41523616, 2025). "The top-ranking transcripts ranked by Manhattan distance included CHCHD2 (also known as MNRR1) and Clusterin (CLU) upregulation, with downregulation of FABP3 and S100A4, modulation, all having previously been associated with neurodegenerative disease;." (PMID 41173878, 2025). "Structurally, pigs possess gyrencephalic brains that resemble the human brain in cortical organization, gray-to-white matter ratios and the expression of biomarkers such as GFAP/clusterin, which are relevant to neurodegenerative diseases." (PMID 40483385, 2025). "The chaperone glycoprotein known as clusterin, or apolipoprotein J, plays a significant role in the pathogenesis of neurodegenerative diseases." (PMID 38184629, 2024). "This process was accompanied by increased expression of CLU, a gene involved in cell death and neurodegenerative diseases, and decreased expression of the immune genes HLA-DRA, HLADRB1 and CD74." (PMID 37275903, 2023). "While the roles of CLU and S100B in neurodegenerative diseases are being debated, we found evidence for the upregulation of neuroprotective effects in cell lines overexpressing these genes, in response to hypoxia and oxidative stress." (PMID 36243678, 2022). "In the case of neurodegenerative diseases, we can highlight the role of CLU in the development of AD." (PMID 35203598, 2022). "Such proteins as Aβ, tau, or α-synuclein, involved in the generation of pathological events in neurodegenerative diseases such as AD and PD, have been demonstrated to be neutralized by clusterin." (PMID 35326174, 2022). "Further evidence for clusterin involvement in the clearance of aberrantly folded proteins comes from the fact that its expression increases in neurodegenerative diseases, where a toxic effect of such protein aggregates has been documented." (PMID 35326174, 2022). "More specifically, we clearly showed in SH-Syn that CLU expression is up-regulated earlier and more strongly than Hsp27, Hsp70, and Hsp90—the chaperones most extensively studied in neurodegenerative diseases." (PMID 33003328, 2020). "Animal studies of clusterin expression in neurodegenerative disease have yielded paradoxical results." (PMID 33192447, 2020). "Increased levels of clusterin have been observed not only in the AD brain but also in other neurodegenerative diseases, including ALS, multiple sclerosis, transmissible spongiform encephalopathies, and Huntington’s disease." (PMID 30872998, 2019).
neurodegenerative disease (continued). "In this review, we discuss the complexity of clusterin and the importance of this protein in the context of neurodegenerative diseases while drawing parallels from other fields, particularly, oncology." (PMID 30872998, 2019). "The dysregulation of other neurodegenerative disease pathways suggests a role for CLU in neurodegeneration processes beyond its direct interaction with Aβ." (PMID 30090055, 2018). "We therefore conclude that increased expression of clusterin can provide an important defense against intracellular proteotoxicity under conditions that mimic specific features of neurodegenerative disease." (PMID 29115989, 2017). "Moreover, CLU is a key player in various pathological conditions, such as cancer, metabolic syndromes, inflammatory disorders, neurodegenerative diseases, and aging-related changes." (PMID 40650133, 2025). "However, CLU expression in astrocytes and neurons is increased during inflammation, stress, or neurodegenerative diseases." (PMID 39627493, 2025). "Remarkably, CLU expression was upregulated earlier and more robustly than other Hsp types, such as Hsp27, Hsp70, and Hsp90, involved in maintaining the protein homeostasis in several neurodegenerative diseases, including PD." (PMID 40650133, 2025). "Accumulating evidence suggests that clusterin’s role as an extracellular chaperone could directly influence the progression of neurodegenerative diseases." (PMID 38184629, 2024). "These consisted of markers of astrocytic and microglial activation (GFAP, vimentin, galectin-1, and clusterin) and indicators of neurodegenerative disease (ApoE and serpinA3N) that each demonstrated significant prion effects and PAM effects from the MS proteomic analysis." (PMID 36378750, 2022). "Clusterin accumulation is found in many different neurodegenerative diseases." (PMID 33192447, 2020). "Considerable genetic evidence connects clusterin to neurodegenerative disease." (PMID 33192447, 2020). "With a client ratio of 1:10 for blocking Abeta amyloid formation, clusterin clearly represents a potent chaperone, and increasing evidence indicates that its extracellular chaperone action may directly impact the course of neurodegenerative disease." (PMID 33192447, 2020). "Whether this endocytic pathway represents a major functional contribution of clusterin in neurodegenerative diseases remains to be established." (PMID 33192447, 2020). "After injury, in inflammatory states, and in neurodegenerative diseases like AD, both neuronal and astrocytic CLU expression is increased, although whether this rise is protective or toxic is unknown." (PMID 30872998, 2019). "Nevertheless, given that protein aggregation is a common pathological hallmark across neurodegenerative diseases, it is not surprising that the chaperone function of CLU has been studied in several proteinopathies." (PMID 30872998, 2019). "Specifically, clusterin is a chaperone which is increased in neurodegenerative diseases." (PMID 28904337, 2017). "In humans, CLU is involved in several neurodegenerative diseases." (PMID 27507242, 2016). "CSF clusterin levels in patients with neurodegenerative disease may aid in diagnosis." (PMID 38184629, 2024). "Therefore, upregulated Clusterin levels may indicate biochemical signs of a neurodegenerative disease." (PMID 27362861, 2016). "A recent preprint suggests that SARS-CoV-2 induces amyloid aggregation of several proteins involved in neurodegenerative diseases such as APLP1, ApoE, clusterin, α2-macroglobulin, PGK-1, ceruloplasmin, nucleolin, 14–3-3, transthyretin, and vitronectin." (PMID 36362302, 2022). "We have examined in this study whether or not increased expression of clusterin is able to protect neuronal cells against intracellular protein aggregation and cytotoxicity, characteristics that are strongly implicated in a range of neurodegenerative diseases." (PMID 29115989, 2017).